PPARG (peroxisome proliferator activated receptor gamma)
Diseases named in the same sentence as PPARG in open-access papers (continued):
Sharing a sentence is not in itself a finding about the gene and the disease.
breast cancer (continued). "It is already known that the expression of PPARγ, as the key regulator of lipogenesis, is altered in breast cancer." (PMID 36230483, 2022). "PPARγ has been shown to function as tumor suppressor in colon, lung, pancreatic, prostate and breast cancer, as increased PPARγ signaling in these diseases leads to reduced cellular growth and the inhibition of tumor invasiveness." (PMID 36142452, 2022). "Intriguingly, application of the PPARγ agonist rosiglitazone in combination with the MEK inhibitor trametinib can terminally differentiate breast cancer cells that have undergone epithelial-mesenchymal transition (EMT) into adipocytes." (PMID 36276273, 2022). "In the following work, we investigated the nuclear peroxisome proliferator-activated receptor gamma (PPARγ)-dependent proliferation behavior of breast cancer cells after stimulation with matcha green tea extract (MTE)." (PMID 35079875, 2022). "For example, melatonin and peroxisome proliferator-activated receptors (PPARγ) agonists synergistically induce apoptosis in breast cancer cells." (PMID 36225557, 2022). "The deletion of PPARγ in macrophages further exacerbated mammary-tumor development in a mouse model." (PMID 35954274, 2022). "Lower expression levels of five hub gens, including IGF1, LEP, ADIPOQ, NR3C1, and PPARG, were determined and were remarkably associated with poorer OS and BCSS among breast cancer patients." (PMID 35317079, 2022). "The expression of PPARγ is inversely correlated with the histological grade of invasive breast cancer and with in situ ductal breast cancer recurrence." (PMID 36611922, 2022). "Taken together, our data suggest that TRIB3 modulates PPARγ-mediated growth inhibition by interfering with the MLL complex in MCF7 breast cancer cells." (PMID 36142452, 2022). "Bonofiglio’s team discovered an important pathway for PPARγ in human breast cancer cell growth, cycle arrest, and apoptosis." (PMID 36611922, 2022). "Some studies have demonstrated that PPARγ is overexpressed in breast cancer, suggesting a possible role in tumor development and/or progression." (PMID 33808259, 2021). "In breast tissues from breast cancer patients, PPARG expression levels were lower in cancer than normal tissues and differed by cancer stage." (PMID 33477496, 2021). "Next, we analyzed PPARγ expression level in ER+ breast cancer patients receiving tamoxifen monotherapy that have an early or late recurrence and found it to be higher in patients who had late recurrence." (PMID 34580286, 2021). "PPARγ physically binds to Nur77 and facilitates ubiquitin ligase Trim13-mediated ubiquitination of Nur77, thereby aggravating breast cancer." (PMID 34775964, 2021). "Expression of peroxisome proliferator-activated receptor gamma (PPARγ), a key regulator of lipogenesis, is altered in breast cancer." (PMID 34631530, 2021). "In fact, recent studies have reported on the use of PPARG as a promising molecular target for specific cancer types, including breast cancer." (PMID 35187064, 2021). "Ligand activation of PPARγ has also been found to exert anti-tumor effects in diverse preclinical models including breast cancer by inducing apoptosis, differentiation, cell growth inhibition and cell cycle arrest." (PMID 34580286, 2021). "PPARγ agonists trigger apoptosis, inhibit cell growth, decrease breast cancer cell motility and inhibit invasion of breast cancer cells." (PMID 34631530, 2021). "It has been largely documented that the induction of extrinsic and intrinsic pathways of apoptotic process is a biological response resulting from PPARγ activation in breast cancer cells." (PMID 34444715, 2021). "In breast cancer, PPARG has been demonstrated with antitumor activities but its mechanism of action still needs further research." (PMID 34567087, 2021). "Breast cancer cell-derived EVs were used to test the effects of peroxisome proliferator-activated receptor-γ (PPARγ) and retinoid X receptor (RXR) agonists on breast cancer spheroids." (PMID 33946403, 2021).
breast cancer (continued). "Activation of peroxisome proliferator-activated receptor γ (PPARγ) was shown to markedly decrease VEGF expression in 4T1 murine breast cancer cells in vitro, and NE was shown to inhibit PPARγ expression in these cells." (PMID 33547275, 2021). "It was established that the level of Peroxisome proliferator-activated receptor γ (PPARG) is related to breast cancer patient prognosis." (PMID 33807872, 2021). "The stimulation by the peroxisome proliferator-activated receptor gamma (PPARγ) pathway has been proposed as a possible mechanistic pathway in the prevention of mammary cancer." (PMID 34698063, 2021). "Our findings account for historical observations of de-novo resistance to PPARγ agonist monotherapy and propound a therapeutically cogent intervention against two aggressive breast cancer subtypes." (PMID 34580286, 2021). "TZDs, PPARγ agonists, can diminish the expression of P450 aromatase in human breast tissue and breast cancer as well as in ovarian granulosa cells." (PMID 34204039, 2021). "Recent studies have suggested an association between Peroxisome proliferator-activated receptor γ (PPARγ) signaling and lapatinib-resistant breast cancer." (PMID 33946495, 2021). "Low level of expression of PPARG was observed in patients with local recurrence and in patients who died of breast cancer." (PMID 33807872, 2021). "A dose-dependent effect, in which increasing concentrations of LBH589 were monotonically associated with the extent of PPARγ upregulation, was also observed in a variety of representative ER+ and triple-negative (TNBC) breast carcinoma cell lines." (PMID 34580286, 2021). "An evaluation of 3 951 breast cancer patients showed that patients with high levels of PPARG expression had a significantly higher survival rate than those with low PPARG expression." (PMID 32850439, 2020). "More studies demonstrate that a number of antineoplastic processes initiated by PPARγ activation in TAMs induce a switch towards a less aggressive phenotype, thus limiting breast cancer progression." (PMID 33352766, 2020). "Recently, it has been demonstrated that the conjugates of DHA with ethanolamine (DHEA) or serotonin (DHA-5-HT) decrease the cytokine secretion by TAMs of breast cancer in a PPARγ-dependent manner, reprogramming TAMs in a less aggressive phenotype." (PMID 32937951, 2020). "The PPI results showed that its key targets for breast cancer include PPARG, TLR-4, BDNF, and PPAR-α." (PMID 33536908, 2020). "On the other hand, PPARγ has been studied extensively for its application in potential breast cancer therapies, but the level of PPARγ expression is significantly higher in human breast cancer tissues." (PMID 33180852, 2020). "A vast scientific literature about the effects of PPARγ agonists in breast cancer is currently available, reflecting the interest in the use of PPARγ ligands in breast cancer management." (PMID 32937951, 2020). "Recently, in breast cancer tissues the expression levels of PPARγ were investigated in relation to many clinicopathological parameters including patient survival." (PMID 33352766, 2020). "It has been reported that sub-saturated doses of the TZDs, troglitazone and rosiglitazone, activate the autophagic flux in a PPARγ-dependent manner through the upregulation of the hypoxia-inducible factor 1 (HIF1)α in MDA-MB-231 breast cancer cells." (PMID 33352766, 2020). "The aim of the present review is to summarize the role of PPARγ activation in breast cancer from the basic research to clinical studies." (PMID 32937951, 2020). "We herein summarize the current knowledge of the role of PPARγ and its natural and synthetic ligands in breast cancer providing an overview from in vitro experiments to in vivo and clinical studies." (PMID 32937951, 2020). "6-Shogaol, the major bioactive compound in the rhizomes of ginger, generates growth inhibition and apoptosis in a PPARγ-dependent manner suppressing NF-κB activity in breast cancer cells." (PMID 33352766, 2020).
breast cancer (continued). "Several studies have been conducted to provide a global view of the functional role of PPARγ in breast cancer since it has been demonstrated that it is over-expressed in several breast cancer cell lines." (PMID 33352766, 2020). "In the following sections, the recent knowledge regarding the effects of PPARγ agonists in breast cancer biology from in vitro experiments to in vivo and clinical studies will be discussed." (PMID 32937951, 2020). "Along the same lines, the important effects of ligand-activated PPARγ in inhibiting the production of the VEGF in tumor endothelial cells should be further explored to counteract breast cancer angiogenesis." (PMID 33352766, 2020). "Ethanolamine derivatives of eicosapentaenoic acid (EPA) and docosahexaenoic acid (DHA) have recently been found to induce autophagy by activating PPARG in human breast cancer cells." (PMID 32265986, 2020). "Over the last decade, much research has focused on the implication of natural and synthetic PPARγ agonists in the negative regulation of breast cancer growth and progression." (PMID 32937951, 2020). "The literature search for relevant articles using the terms “PPARγ” AND “breast cancer” was performed in Pubmed database." (PMID 33352766, 2020). "In particular, ligand-activated PPARγ triggers autophagy in breast cancer cells regulating the expression of key molecules involved in this process." (PMID 33352766, 2020). "Activation of peroxisome proliferator-activated receptor gamma (PPARγ) elicits anti-proliferative effects on different tumor cells, including those derived from breast cancer." (PMID 31936729, 2020). "Recently, by using an in vivo and in vitro approach and supported by bioinformatic data, the tumor suppressor role of PPARγ has been deciphered in breast cancer." (PMID 33352766, 2020). "Further investigations have demonstrated that activation of PPARγ can counteract breast cancer cell invasion and migration." (PMID 33352766, 2020). "Recent studies have shown that PPARG has a tumor suppressor effect and can inhibit the proliferation, migration, and invasion of breast cancer cells." (PMID 33536908, 2020). "Recently, one study reported that PPARγ is a direct target of miR-155 that has been found encapsulated in exosomes from breast cancer patients." (PMID 33352766, 2020). "In contrast to these studies, Tian and coworkers demonstrated that activated PPARγ promoted tumor angiogenesis and growth in breast cancer." (PMID 32785018, 2020). "Mainly, they revealed that fibroblasts overexpressing PPARγ become autophagic, senescent and glycolytic and produce metabolites which are used by breast cancer cells to increase their mitochondrial capacity and their proliferative ability." (PMID 33352766, 2020). "In early research papers, it was shown that PPARγ activation induces growth inhibition in colon and breast cancer cell lines." (PMID 32012980, 2020). "In our search for novel TAM-modulating agents, we tested the effects of natural and synthetic PPARγ agonists on the capacity of the breast cancer cell secretome to modulate macrophage polarization." (PMID 31936729, 2020). "Our research group also showed the antiproliferative effects of DHEA on breast cancer cell lines through PPARγ activation." (PMID 31936729, 2020). "It has been largely documented that induction of different pathways of apoptotic process is a biological response resulting from PPARγ activation in breast cancer cells." (PMID 32224850, 2020). "Evidence also support that PPARγ activation results in inhibition of breast tumor growth either in vivo models or in vitro breast cancer cells." (PMID 32937951, 2020). "Subsequently, we explored the effects of PPARγ activation on macrophage polarization induced by breast cancer cells." (PMID 31936729, 2020).
breast cancer (continued). "The interaction between PPARγ and mTOR has been particularly well demonstrated in mouse models of breast cancer, in which the activation of PPARγ led to rapamycin resistance, whereas rapamycin treatment triggered both the expression and activation of PPARγ." (PMID 32708786, 2020). "In another elegant work, a link between PPARγ and parvin-β, a protein downregulated in breast cancer cells, has been described." (PMID 33352766, 2020). "Deletion of PPARγ in the mammary epithelium promoted mammary stem cell (MSCs) expansion favoring angiogenesis and breast cancer growth." (PMID 32785018, 2020). "In earlier studies we found that DHA-derived compounds inhibit breast cancer progression and development through PPARγ activation." (PMID 31936729, 2020). "Corresponding clinical studies have also confirmed that among breast cancer patients, those with high PPARG expression levels have a higher survival rate than patients with low PPARG expression levels." (PMID 33536908, 2020). "Conversely, adiponectin, whose expression is regulated by PPARγ activated transcriptional program, is decreased in both in vitro co-culture models and in CAAs of human breast cancer tissues as compared with normal mammary adipose tissue." (PMID 33352766, 2020). "Specifically, both couples of n-3 PUFA conjugates were PPARγ-inducers able to activate the endogenous PPARγ and to upregulate its expression triggering autophagy in breast cancer cells." (PMID 32224850, 2020). "We have previously demonstrated, for the first time, that DHEA through PPARγ activation induces cell growth inhibition, triggering autophagy in breast cancer cells." (PMID 31936729, 2020). "Clinical studies revealed that PPARγ expression represents a positive prognostic factor in luminal and ductal breast cancer patients, since higher levels of PPARγ inversely correlate with grade, tumor size, and TNM staging system of malignant tumor." (PMID 32937951, 2020). "They found that thymoquinone can increase PPARγ activity and downregulate the expression of Bcl2 and Bcl-xL in breast cancer." (PMID 33197888, 2020). "Synthetic PPARγ agonists, including the antidiabetic drugs thiazolidinediones (TZDs), demonstrated to induce growth inhibition, apoptosis, and differentiation of breast cancer cells in in vitro and in vivo models." (PMID 32937951, 2020). "It has been described how breast cancer cells over-expressing miR-155 exhibited a down-regulation of PPARγ expression and, consequently, decreased lipid droplets in mature adipocytes." (PMID 33352766, 2020). "PPARγ agonists have been successfully used to desensitize TAMs to lactate stimulation with antitumor effects in breast cancer." (PMID 31936729, 2020). "Rapamycin resistance can be obtained by PPARγ activation, whereas treatment with rapamycin increases both expression and activation of PPARγ in mouse models of breast cancer." (PMID 33198317, 2020). "The present study and other research showed that PPARG acted as a tumor suppressor and was demonstrated to suppress cell proliferation, migration, and invasion in breast cancer." (PMID 32850439, 2020). "PPARG has been shown to increase the chemosensitivity in several human carcinomas, including nonsmall-cell lung carcinoma, breast carcinoma, and pancreatic carcinoma." (PMID 32373170, 2020). "Multiple lines of evidence indicate that activation of the peroxisome proliferator-activated receptor γ (PPARγ) by natural or synthetic ligands exerts tumor suppressive effects in different types of cancer, including breast carcinoma." (PMID 33352766, 2020). "In basal-like breast carcinoma, PPARG activation significantly reduces the expression of MnSOD and increases chemosensitivity." (PMID 32373170, 2020).
breast cancer (continued). "In contrast, antagonist of PPARγ inhibits breast cancer cell growth and increases E2-induced apoptosis via regulation of oxidative stress and NF-κB-dependent TNFα expression." (PMID 31815253, 2019). "The pro-tumorigenic and anti-tumorigenic role of PPARG was also found in colon cancer, breast cancer, prostate cancer, lung cancer and many others." (PMID 30845932, 2019). "For breast cancer, the PPARγ agonist GW7845 can inhibit N-nitroso-N-methylurea-induced breast cancer in rats and treatment with troglitazone can also alleviate breast cancer induced by 7,12-dimethylbenz[a]anthracene (DMBA) in mice." (PMID 31336903, 2019). "PPARA and PPARG are also involved in the regulation of cholesterol metabolism, which was shown to regulate cell adhesion in breast cancer cell lines." (PMID 30974831, 2019). "A recent study reported that cannabidiol-induced apoptosis of breast cancer cells by downregulation of mTOR and cyclin D1, and upregulation PPARγ." (PMID 31075907, 2019). "Consistently, treatment by LY294002, a specific PI3K inhibitor and troglitazone (TGZ), a PPARγ agonist, known to exhibit anti-proliferative activity in breast cancer cells both achieved a significant reduction of H1 tyrosine phosphorylation in MCF7." (PMID 31816600, 2019). "PPARγ's expression has been reported to be deregulated in breast cancer patients, along with other cancer types." (PMID 31511776, 2019). "Thiazolidinediones, the class of drugs known as peroxisome proliferator-activated receptor-γ (PPARγ) agonists, were considered effective drugs for breast cancer metastasis." (PMID 29316690, 2018). "A pertinent work showed the suppressive effects of PPARγ antagonism in populations of cancer stem cells (CSCs) derived from ERBB2-positive breast cancer cell lines (BT474 and SKRB3)." (PMID 29966227, 2018). "Several studies have revealed the activities of marine natural products in inhibiting inflammation in leukemia cells and in inducing apoptosis in breast cancer cells via PPARγ activation." (PMID 30018246, 2018). "Further research to investigate the major factors in lipid metabolism and interventional research of targeting PPARγ in breast cancer are needed." (PMID 30305115, 2018). "PPARγ activation has been shown to inhibit proliferation and induce cell cycle arrest in breast cancer cells." (PMID 30456386, 2018). "For example, E2 upregulates PPARG expression in adipocytes, but E2 suppresses PPARG transcription via binding competitively to shared transcriptional factors in human breast cancer cells." (PMID 30510575, 2018). "Of note, PPARγ was reported to suppress glycolysis and induce apoptosis in breast cancer cells by repressing the expression of several glycolytic enzymes." (PMID 30456386, 2018). "PPARγ is expressed in various malignant tissues, including bladder, colon, prostate, and breast cancer." (PMID 29599799, 2018). "Compared with normal controls, the expressions of FAK, Src, ERK1/2 and Stat3 are up-regulated, while the expressions of PPARγ, C21orf34 and E-cadherin are down-regulated in TCGA Breast Cancer and Turashvili Breast Cancer." (PMID 28108732, 2017). "As indicated by data from Oncomine database, compared with normal controls, the expressions of FAK, Src, ERK1/2, Stat3 mRNA increased, while the expressions of PPARγ, C21orf34 and E-cadherin decreased in human melanoma cancer and breast cancer." (PMID 28108732, 2017). "VDR, RXR and PPARγ were detected in over 90% of triple negative BRCA1mut breast cancer and were significantly (VDR: p < 0.001, RXR: p = 0.010, PPARγ: p < 0.001) overexpressed in BRCA1 mutated as compared to sporadic cancer cases." (PMID 28427429, 2017). "We also analyzed the mRNA level of FAK, Src, ERK1/2, PPARγ, C21orf34, Stat3 and E-cadherin in human breast cancer using Oncomine Cancer Microarray database." (PMID 28108732, 2017).